CIITA (class II major histocompatibility complex transactivator)
Diseases named in the same sentence as CIITA in open-access papers (continued):
Sharing a sentence is not in itself a finding about the gene and the disease.
colorectal cancer (8 papers, 2018 to 2025). A primary or metastatic malignant neoplasm that affects the colon or rectum. "Colorectal cancer cells are also susceptible to genetic and epigenetic abnormalities, including changes in DNA methylation that affect CIITA expression." (PMID 30319613, 2018). "The treatment interaction analysis for certain SNPs such as for ERAP1 and CIITA showed interaction with oxaliplatin, which has been shown to cause immunogenic cell death in colorectal cancer cells and upregulate MHC class I via the nuclear factor-kappa B (NF-κB) pathway." (PMID 40141198, 2025). "In colorectal cancer cells, for instance, promoter methylation of the class II transactivator (CIITA) gene impairs IFN-γ-induced CIITA expression, thereby blocking MHC class II upregulation and reducing CD4+T cell recognition." (PMID 40805243, 2025). "In colorectal cancer, tsMHC-II negativity is common, in cell lines due to CIITA promoter methylation." (PMID 37565053, 2023). "IL-27 elevates CIITA levels in colorectal cancer cells and stimulates endothelial cells in vitro to express HLA-DR, -DP, -DQ, -DM, and invariant chain." (PMID 30319613, 2018). "Thus, CIITA methylation is likely to be a 2D cell culture–mediated phenomenon and does not appear to be a relevant mechanism for silencing tsMHC-II in colorectal cancer." (PMID 37565053, 2023). "Moreover, sequentially immunostained sections of colorectal carcinoma (n = 5) and matched normal mucosa showed decreased expression of CIITA in CD163+ macrophages compared to normal tissue." (PMID 34680345, 2021). "Our results indicated that CIITA might play a crucial role in the prognosis of colorectal cancer." (PMID 37427112, 2023). "For this reason, we screened 7 m6A-related genes (IL12RB1, FASLG, CXCL13, GBP2, CXCL10, CXCR6, and CIITA) through WGCNA and LASSO regression in this study and established an m6A-GPI in colorectal cancer." (PMID 37427112, 2023). "There is further confirmatory evidence in colorectal cancer, with tissue microdissection from primary tissue samples failing to find any evidence of CIITA promoter methylation in 20 tsMHC-II negative tumors." (PMID 37565053, 2023). "On the basis of the previously observed frequency (3/8) of 2D colorectal cancer cell lines demonstrating CIITA methylation, this result of zero of 15 organoids nonmethylated is highly significant (probability-based P = 0.0009; Fisher exact P = 0.032)." (PMID 37565053, 2023). "Together, these findings in 3D and primary colorectal cancer samples confirm that CIITA methylation is not a biologically relevant route of immune evasion in colorectal cancer and is likely to be a culture-induced aberrant methylation pattern." (PMID 37565053, 2023). "Given this proimmune impact of tsMHC-II expression, one of the immunologic escape mechanisms that colorectal cancer cells might utilize is cell-autonomous transcriptional repression of CIITA and consequent noninducibility of tsMHC-II by IFNγ." (PMID 37565053, 2023). "In colorectal cancer cell lines, noninducibility has been attributed to CIITA promoter methylation." (PMID 37565053, 2023).
diffuse large B-cell lymphoma (8 papers, 2015 to 2024). "Next-generation sequencing using a lymphoma panel for diffuse large B-cell lymphomas revealed frequent genetic losses in CIITA, as in previous cases, this loss may participate in the immune escape." (PMID 33499042, 2021). "For instance, entinostat, an HDACi increased the level of MHC class II-mediated antigen presentation by transcriptional activation of Class II Major Histocompatibility Complex Transactivator (CIITA) in diffuse large B cell lymphoma (DLBCL)." (PMID 37808081, 2023). "Gene alterations occurring during cancer development can negatively regulate HLA expression, for example damage to the class II transactivator (CIITA) gene, or large chromosomal deletions, as observed in diffuse large B cell lymphomas originating from immune-privileged sites." (PMID 32306077, 2020). "Additionally, it has been demonstrated that entinostat increased the level of MHC II by transcriptional activation of CIITA in diffuse large B cell lymphoma (DLBCL)." (PMID 28572863, 2017). "We obtained similar results in SUDHL4 cells, a diffuse large B-cell lymphoma (DLBCL) cell line, where CIITA pIII is constitutively expressed (Fig. EV5A–C)." (PMID 39562739, 2024). "In a previous study, following treatment with the HDAC-1-specific inhibitor MS-275, the expression of CIITA and MHC class II in diffuse large B-cell lymphoma (DLBCL) cells was upregulated." (PMID 25815463, 2015). "Genetic aberrations affecting CIITA are also enriched in GCB-DLBCL, DLBCL with plasmacytic differentiation, and EBV-positive diffuse large B-cell lymphoma (EBV+DLBCL)." (PMID 36765793, 2023).
multiple sclerosis (8 papers, 2012 to 2024). A progressive autoimmune disorder affecting the central nervous system resulting in demyelination. "In a recent article addressing the influence of CIITA and HLA-DRB1 in multiple sclerosis, a complex risk relationship between these loci is presented." (PMID 22461888, 2012). "Specifically, the TF with the highest weight in the TF-expression model (β = 0.23 in muscle and β = 0.18 in blood) is CIITA, where variability in the CIITA gene has been reported to interact with specific mutations of HLA-DRB1 to increase the risk for multiple sclerosis and type 1 diabetes." (PMID 35627314, 2022). "In our differential expression list, CIITA is a key regulator of MHC II expression, which mediates antigen presentation and the reactivation of CNS-infiltrated encephalitogenic T cells in experimental allergic encephalomyelitis and multiple sclerosis." (PMID 32209134, 2020). "Interestingly, this putativeimmuno-receptor, which belongs to a gene complex involving CIITA and SOCS1, islinked to autoimmune disorders such as multiple sclerosis and rheumatoid arthritis." (PMID 25520755, 2014).
gastric cancer (7 papers, 2012 to 2025). A primary or metastatic malignant neoplasm involving the stomach. "In colorectal and gastric cancer, the reactivation of CIITA activates the immune system and contributes to the anti-tumor immune response." (PMID 33763372, 2021). "These include histone deacetylation of the CIITA pIV in squamous cell carcinomas and rhabdomyosarcomas, and hypermethylation of the CpG islands in CIITA pIV colon and gastric carcinoma lines." (PMID 24475282, 2014). "Major histocompatibility complex class II is linked to better prognosis of cancer patients, and its expression on cancer cells depends on the trans activator CIITA, which is inactivated in colorectal and gastric cancers, hence attributing tumour suppressor function to CIITA." (PMID 35409426, 2022). "In trophoblasts, expression of CIITA is blocked by CIITApIV start site proximal DNA methylation and DNA methylation at regions 2 and 3 of the 5′ CIITApIV CpG island has been detected in colorectal and gastric cancers which lack CIITA expression." (PMID 22563434, 2012). "Using RNA-seq data from 400 gastric cancer patients, the upregulation of all MHC-II involved genes, including CIITA and RFX5, was observed compared to normal tissues or other types of gastric cancers." (PMID 33499042, 2021). "Furthermore, DNA methylation that selectively represses CIITA, in colorectal and gastric cancer cell lines, was associated with the absence of IFN-γ-induced HLA-DR, suggesting that this epigenetic alteration of CIITA enables some gastrointestinal cancer cells to evade the immune system." (PMID 29780381, 2018). "The master regulator of HLA class II antigens CIITA and both variant and invariant HLA class II chains displayed a decreased mRNA expression in CDX2-induced gastric cancers compared with gastric cancers with no CDX2 induction." (PMID 40149431, 2025).
Sepsis (7 papers, 2011 to 2025). Sepsis is defined as life-threatening organ dysfunction caused by a dysregulated host response to infection. "For the first time, our study reveals reduced expression of MHC-II- and CIITA genes associated with specific changes in binding of CTCF in the intergenic region in critically ill patients suffering from sepsis." (PMID 30212590, 2018). "A low expression level of mRNA encoding CIITA, the major transactivator of HLA-DR gene expression, represents indirectly a transcriptional downregulation of HLA-DR genes in patients with sepsis." (PMID 24093602, 2013). "Increased CTCF binding persisted in all sepsis patients, while transcriptional recovery CIITA was exclusively found in long-term survivors." (PMID 33939725, 2021). "In previous work, the CIITA promoter located on the short arm of chromosome 16 displayed a marked reduction of the histone marks H3K4me3 and H3K27ac in patients with sepsis compared to healthy control individuals." (PMID 33939725, 2021). "This association is related to the expression of Major Histocompatibility Complex II (MHC-II), along with Class II Major Histocompatibility Complex Transactivator (CIITA), also identified as a master regulator of Pediatric Sepsis 1 and 2 networks." (PMID 34680414, 2021). "The aims of this study were to investigate if qRT-PCR measurement of HLA-DRA and CIITA was robust in terms of reproducibility, and if the changes in gene expression reflected shifts in mHLA-DR during the course of sepsis." (PMID 27144640, 2016). "According to our results, dynamic variations in HLA-DRA and CIITA gene expression can be reliably detected during the course of sepsis." (PMID 27144640, 2016). "This difference may be related to several other factors that regulate monocyte HLA-DR in sepsis, including the activity of the Class II transactivator (CIITA) and glucocorticoids (via the suppression of CIITA transcription)." (PMID 41573541, 2025). "Interestingly, we detected a reconstitution of CIITA expression levels at T2 in those patients who survived sepsis within the first year after diagnosis." (PMID 33939725, 2021). "Even more importantly, the observed reduction in classical HLA-DRA, HLA-DRB1, HLA-DPA1 and HLA-DPB1 transcription as well as the decline in monocyte HLA-DR surface expression persisted in all patients with postoperative sepsis despite a recovery of CIITA transcription levels during the study period." (PMID 33939725, 2021). "Moreover, an inverse correlation of CTCF and CIITA expression was detected in patients with postoperative sepsis (R2 = 0.48; p<0.05)." (PMID 33939725, 2021). "In line, we and others could demonstrate that reduced CIITA transcription during sepsis is accompanied by decreased HLA-DR mRNA levels as well as a reduced monocyte HLA-DR receptor density." (PMID 33939725, 2021). "Lower membrane-associated HLA-DR in patients with sepsis, both at baseline and following ex vivo phagocytosis, is associated with a lower expression of proteins associated with antigen presentation, such as class II-associated Ii peptide (CLIP) and HLA-DM, despite higher levels of CIITA and FCγ-R1." (PMID 41573541, 2025). "Hence we speculate that CIITA recovery might serve is an early indicator for a recovery of immune function after sepsis." (PMID 33939725, 2021). "Gene expression analysis revealed a sepsis-associated decreased transcription of (i) the classical HLA genes HLA-DRA, HLA-DRB1, HLA-DPA1 and HLA-DPB1 and (ii) the gene of the MHC-II master regulator, CIITA (Class II Major Histocompatibility Complex Transactivator)." (PMID 33939725, 2021). "Our results are in line with an earlier study uncovering decreased expression of MHC-II- and CIITA genes in peripheral whole blood samples from septic patients as well as own published work and provide further insights on the impact of sepsis on monocyte MHC-II regulation." (PMID 30212590, 2018).
Sepsis (continued). "The transactivator of HLA-DRA gene transcription, a Class II transactivator (CIITA), was also found to be downregulated, and it is possible that HLA-DRA is under transcriptional control in sepsis." (PMID 27144640, 2016). "In this prospective study we evaluated dynamic changes in mHLA-DR expression during sepsis in relation to changes in HLA-DRA gene expression and Class II transactivator (CIITA), measured by quantitative Real-Time Polymerase Chain Reaction (qRT-PCR)." (PMID 27144640, 2016). "In patients with sepsis (n = 59), blood samples were collected simultaneously for HLA-DR monitoring by qRT-PCR (transcripts of HLA-DRA and CIITA) and flow cytometry." (PMID 24093602, 2013). "Nevertheless, in order to be useful as biomarkers in sepsis, any method for measuring HLA-DRA and CIITA, expressed as a ratio to a reference gene, in this case peptidylpropylisomerase gene (PPIB), should be validated regarding its robustness during the course of sepsis." (PMID 27144640, 2016). "HLA-DRA and CIITA decreased to a greater extent in the “severe sepsis/septic shock” group and to a lesser extent in the “non-severe sepsis” group, than did mHLA-DR measured by flow cytometry." (PMID 27144640, 2016). "The mean difference of mHLA-DR, HLA-DRA and CIITA between severity groups (severe sepsis and septic shock/non-severe sepsis), calculated on logarithmic scale, expressed as ratios and presented at each time point." (PMID 27144640, 2016). "In pairwise testing of the differences between blood donors and septic patients at each time point, all biomarkers showed downregulated values until day 14 in the “severe sepsis/septic shock” group, although HLA-DRA and CIITA showed a greater magnitude of downregulation." (PMID 27144640, 2016). "In addition, we monitored by qRT-PCR the expression of five genes described in the literature to be involved in the ET refractory state or sepsis-induced immunosuppression (HLA-DRA, CIITA, IRAK-M, ABIN-3, and LY64)." (PMID 22027436, 2011). "However, we found that reduced CIITA transcription in patients with postoperative sepsis was not accompanied with a general HLA class II downregulation." (PMID 33939725, 2021). "This is also in line with a previously conducted study of our group and supports the assumption that the proposed interaction between CIITA, CTCF and its binding sites might be disturbed during critical illness like sepsis, resulting in a decoupled co-regulation of HLA genes." (PMID 33939725, 2021). "However, in a previous study, we could demonstrate specific changes in histone modifications and found sepsis-induced alterations in both MHC-II locus and CIITA gene of isolated CD14++ CD16—monocytes." (PMID 30212590, 2018). "In particular, mHLA-DR discriminated between severe and non-severe sepsis in the early stage of sepsis only, while HLA-DRA- and CIITA-mRNA levels measured by qRT-PCR, showed prolonged divergence between our severity groups." (PMID 27144640, 2016).
Autoimmunity (6 papers, 2010 to 2025). The occurrence of an immune reaction against the organism's own cells or tissues. "Although there is evidence of potential interaction between SNPs in CIITA and HLA alleles in autoimmunity, the promoter SNP rs3087456 alone appears to predispose neither to myasthenia gravis nor to autoimmunity in general." (PMID 20942939, 2010). "In view of its suggested role in autoimmune disorders, we sought to determine if the CIITA rs3087456 variant is associated with autoimmune MG, using a large cohort of Swedish patients." (PMID 20942939, 2010). "Summary of published CIITA SNP rs3087456 association studies in autoimmune disorders." (PMID 20942939, 2010). "This is unlikely to be relevant to RA, but less severe changes in efficiency of CIITA expression might be important for autoimmunity development and statistical evaluation of genetic interaction of CIITA and shared epitope alleles may reveal “missing” risk factors." (PMID 22461888, 2012). "CIITA, which encodes the major histocompatibility complex (MHC) class II transactivator and SOCS1 that encodes suppressor of cytokine signalling 1, both have functions of importance for autoimmunity." (PMID 39940946, 2025). "SOCS1 and CIITA are recognized contributors to inflammation and autoimmunity." (PMID 38022642, 2023). "The lack of allelic association of the CIITA SNP -168A→G (rs3087456) with MG casts further doubt on the presumed role of this particular SNP in autoimmune disorders." (PMID 20942939, 2010). "We thus conclude that previous findings with regard to the role of the CIITA -168A→G SNP in autoimmunity may have to be reconsidered." (PMID 20942939, 2010). "Two immune-regulatory genes of potential interest for autoimmunity i.e., the major histocompatibility complex (MHC) class II transactivator (CIITA) gene and the suppressor of cytokine signaling 1 (SOCS1) gene, are located close to CLEC16A." (PMID 33795715, 2021).
colon carcinoma (6 papers, 2020 to 2025). "HLA class II-negative tumors containing mutations in HLA class II regulatory genes, such as CIITA, were found to be significantly more likely to develop microsatellite-unstable colon carcinomas." (PMID 37046620, 2023). "For instance, research has shown that IFN-γ induces transcription at the CIITA-pIV site in colon cancer cells, while treatment with TSA induces transcription at the CIITA-pIII site." (PMID 40573881, 2025). "Constitutive CIITA expression is normally confined to antigen-presenting cells and it was thus striking to find CIITA and MHC Class II genes expressed in Fbw7 mutated colon cancer cells and NSCs." (PMID 35225231, 2022). "Thus, even in a single murine colon cancer cell line, pathways converge that are CIITA-dependent and CIITA-independent." (PMID 38915093, 2024). "A colon cancer cell line lacking DNMT1 and DNMT3b exhibited reduced methylation on CIITA-PIV, implicating a role for DNMTs in CIITA regulation." (PMID 38915093, 2024).
HIV-1 infection (6 papers, 2013 to 2024). The type species of lentivirus and the etiologic agent of acquired immunodeficiency syndrome (AIDS). "Although it can be hypothesized that antigen-specific CD4+ cell activation may also generate new targets for HIV-1 infection, the risk of propagating productive infection is largely counterbalanced by CIITA expression, as a potent HIV-1 restriction factor, strongly inhibiting virus replication." (PMID 29385169, 2018). "Several years ago, we discovered that CIITA restricts HIV-1 infection by acting at the level of viral replication." (PMID 23986750, 2013). "Although U937 cell clones differ for the expression of CIITA, we cannot exclude that other factors could contribute to their divergent capacity to sustain productive HIV-1 infection." (PMID 27089879, 2016). "In addition, these results indicated that this cellular model represented by isogenic cell clones naturally differing for CIITA expression is suitable to define the anti-viral role of this molecule in HIV-1 infection of myeloid cells." (PMID 27089879, 2016). "We previously found that the different susceptibility to HIV-1 infection in the two isogenic promonocytic U937 cell Minus and Plus clones was associated with the expression of both CIITA and TRIM22 restriction factors in Minus cells but not in HIV-1 permissive Plus cells." (PMID 39205150, 2024). "The different susceptibility to HIV-1 infection in U937 cells—permissive (Plus) or nonpermissive (Minus)—is linked to the expression in Minus cells of interferon (IFN)-γ inducible antiviral factors such as tripartite motif-containing protein 22 (TRIM22) and class II transactivator (CIITA)." (PMID 39205150, 2024). "Besides its prominent role in the regulation of adaptive immune response, the first evidence that CIITA may act as an RF emerged in the context of HIV-1 infection, when we found it was acting as negative transcriptional regulator of HIV-1 expression in T cells." (PMID 31783769, 2019).